INS (insulin)
Diseases named in the same sentence as INS in open-access papers (continued):
Sharing a sentence is not in itself a finding about the gene and the disease.
type 2 diabetes (continued). "We previously investigated the correlation between the serum ucOC concentrations and secretory ability of insulin in patients with type 2 diabetes." (PMID 31050684, 2019). "Insulin glargine U100 is a cost-effective treatment for patients with type 2 diabetes compared to NPH insulin in setting in Hong Kong." (PMID 31303866, 2019). "Evidence has it that low dietary intake of antioxidants such as β-carotene, α-tocopherol, and vitamin E play independent roles in the pathogenesis of Type 2 diabetes by increasing insulin resistance or impairing insulin action." (PMID 31803711, 2019). "The concentrations of inflammatory mediators in the serum are elevated in the insulin-resistant states of obesity and type 2 diabetes." (PMID 31504048, 2019). "Type 2 diabetes is characterized by progressive impairment of insulin sensitivity, followed by beta-cell dysfunction." (PMID 31737067, 2019). "The predicted targets of this inflammation-related miRNA42 were seen to be enriched in the insulin signaling and type II diabetes mellitus pathways." (PMID 31222113, 2019). "Nagao and Yanagita, (2010), reported medium-chain triglycerides (MCTs) and medium-chain fatty acids (MCFAs) have a therapeutic advantage in preserving insulin sensitivity as found in animal models and patients with type 2 diabetes." (PMID 30823426, 2019). "They found that a small number of obese population showed insulin resistance at the beginning of type 2 diabetes, while most of population had decreased insulin secretion." (PMID 30833619, 2019). "It is well known that high meat intake, specifically red and processed meat, are associated with higher prevalence of metabolic syndrome, impaired insulin sensitivity, type 2 diabetes, and oxidative stress." (PMID 31623368, 2019). "They concluded that replenishing Vitamin D in patients with type 2 diabetes and established hypovitaminosis D improve glycemia and insulin secretion, thereby suggesting a role for vitamin D in the pathogenesis and management of type 2 diabetes mellitus." (PMID 31412921, 2019). "It results from the inability of body to produce enough insulin (type 1 diabetes) or the failure to respond efficiently to the insulin produced by the pancreatic beta cells (type 2 diabetes)." (PMID 30838017, 2019). "The present study was conducted with the aim to assess the impact of mealtime fast-acting insulin aspart therapy on GV after switching from regular human insulin in advanced chronic kidney disease patients with type 2 diabetes." (PMID 31886089, 2019). "Previous studies have found that DIM can improve type 2 diabetes by enhancing glucose uptake through the activation of insulin signaling in 3T3-L1 cells, and by lowering the plasma glucose levels in high-fat-diet-fed obese mice." (PMID 31817632, 2019). "In this context, the bile acid TUDCA has emerged as an important candidate due to its known benefits for type 2 diabetic patients, improving the insulin sensitivity in their peripheral tissues." (PMID 31156453, 2019). "IL-10 also has efficacy in insulin sensitivity and glucose tolerance in type 2 diabetes with obesity." (PMID 31828157, 2019). "In individuals with type 2 diabetes, the ability of insulin to stimulate skeletal muscle glucose transport is impaired." (PMID 31614762, 2019). "Observational studies have demonstrated improved insulin sensitivity and reduced incidence of type 2 diabetes with HCV viral clearance." (PMID 31363776, 2019). "The lives of many of type 1 diabetics are dependent on daily insulin injections, which is also necessary for many type 2 diabetic patients." (PMID 30747103, 2019). "It has been shown previously that a plant-based diet increases the proportion of linoleic acid (C18:2) in serum phospholipids, and that this increase was related to increased insulin sensitivity in patients with type 2 diabetes." (PMID 30871233, 2019).
type 2 diabetes (continued). "In type 2 diabetes, HDL-TG was positively related to glucose and insulin levels stressing its direct association to metabolic alterations." (PMID 31694246, 2019). "Type 2 diabetes mellitus (T2DM) represents a chronic metabolic disease characterized by a relative insulin deficiency due to pancreatic β-cell dysfunction and insulin resistance in target organs, with consequent hyperglycemia." (PMID 31205450, 2019). "Type 2 diabetes (T2D) affects more than 90% of all the diabetic patients, and is a long-term malady of food metabolism bring about due to declined insulin function." (PMID 31384754, 2019). "GLP-1 or its analogs have been demonstrated to improve insulin sensitivity in animal models and human type 2 diabetic patients." (PMID 31949438, 2019). "Rosiglitazone, a PPARγ ligand, is used for treatment of type 2 diabetes primarily due to its insulin-sensitizing property." (PMID 31249661, 2019). "One of the problems for people with type 2 diabetes is that they release less insulin into the bloodstream." (PMID 31099751, 2019). "Type 2 diabetes (T2D), which is defined as a group of metabolic disorders characterized by both insufficient insulin secretion and insulin resistance, is a major subtype of diabetes and accounts for more than 90% of it." (PMID 31449493, 2019). "For people with type 2 diabetes (T2D), the frequency of hypoglycemia varies by treatment, with hypoglycemia occurring most frequently with insulin therapy." (PMID 31138204, 2019). "Here, we describe a patient with type 2 diabetes with insulin allergy in which severe DKA resolved after the initiation of continuous intravenous (IV) recombinant human insulin infusion." (PMID 31711488, 2019). "These methods have also been employed in current investigations on the structure and function of insulin secreting beta cells under normal and pathological conditions that lead to an impaired glucose tolerance and type 2 diabetes." (PMID 31627330, 2019). "The aim of this study was to observe the weight change in a patient with type 2 diabetes initiated on insulin therapy and the relation of weight gain with caloric intake." (PMID 31576267, 2019). "Taken together, we identified a phosphoinositide switch on the surface on insulin granules that is required for stable granule docking at the plasma membrane and impaired in human type 2 diabetes." (PMID 31533953, 2019). "In the treatment of type 1 and type 2 diabetes, insulin analogs have shown high efficacy and easy application than human insulin." (PMID 31555212, 2019). "Any decrease in zinc levels can affect the ability of the islet of Langerhans cell to produce and secrete insulin, and compound the problem, particularly in type II diabetes." (PMID 30642010, 2019). "Accordingly, a sex distinction in the type 2 diabetes phenotype has been shown in black Africans, whereby men display greater insulin sensitivity compared with women." (PMID 30729259, 2019). "Several reports have demonstrated that a dose of 500 mg/kg of NMN successfully increased liver NAD+ levels, prevented glucose intolerance in type 2 diabetes, improved insulin sensitivity, and prevented aging-related symptoms through multiple mechanisms." (PMID 31823815, 2019). "When the incretin hormone glucagon-like peptide-1 (GLP-1) was subsequently shown to account for up to 70% of insulin secretion in response to nutrient intake, its potential as a therapeutic target in type 2 diabetes (T2D) was realized." (PMID 31031702, 2019). "Metformin is an inexpensive insulin-lowering drug with an excellent safety profile, which has made it the most prescribed drug for type II diabetes." (PMID 30728358, 2019). "In two recent studies of subjects with type 2 diabetes, circulating levels of miR-483-5p were found to correlate with fasting insulin levels, HbA1c, and a measure of insulin-sensitivity as well as with fasting insulin levels and body mass index (BMI)." (PMID 31590432, 2019).
type 2 diabetes (continued). "Insulin therapy initiation has long been delayed in most of the type 2 diabetics because of its weight-gaining potential, especially for those who are already obese." (PMID 31576267, 2019). "Type 2 diabetes is generally characterized by insufficient secretion of insulin from pancreatic β-cells, combined with impaired insulin sensitivity of peripheral tissues." (PMID 31022842, 2019). "Insulin therapy is used in the treatment of type 1 diabetes (T1D), and less commonly in the treatment of type 2 diabetes (T2D)." (PMID 31584770, 2019). "Insulin glargine U100 is a cost-effective treatment for patients with type 2 diabetes when compared with NPH insulin in the Asian setting in Hong Kong." (PMID 31303866, 2019). "Taken together, studies conducted to date indicate that LADA, similar to type 2 diabetes, results from an imbalance between insulin sensitivity and insulin secretion." (PMID 30971952, 2019). "Most health care providers (91.1%, 95% CI 84.8–97.3; P < 0.0001) preferred the patch to pen to advance subjects with type 2 diabetes from basal to basal–bolus insulin." (PMID 31025878, 2019). "Meanwhile, the insulin signaling pathway is primarily involved in the pathogenesis of human obesity and type 2 diabetes, conditions that are known to facilitate the development of several cancers, including GC." (PMID 31422382, 2019). "For over a dozen years, research has been undertaken to assess the effectiveness of insulin therapy in people with type 2 diabetes based on adjusting insulin doses to meals." (PMID 30871141, 2019). "This study aimed to observe the hypoglycemic effect of cassia seed extract in rats with type 2 diabetes and its effect on reducing insulin resistance in the skeletal muscle." (PMID 31890042, 2019). "One is that the development of DPP-4 inhibition is a rational drug design based in scientific studies on pathophysiology of type 2 diabetes and that the development shows that it is important to target both the impaired insulin secretion and the high glucagon." (PMID 31275243, 2019). "Actually, insulin therapy is suggested for type 2 diabetes patients who have a poor beta-cell reserve, which means decompensation and is not necessarily accompanied by hyperinsulinemia." (PMID 31200528, 2019). "Since type 2 diabetes is a heterogenous disease, we focused on young adult patients with type 1 diabetes to assess the influence of the exogenous insulin dose on the ucOC and OC concentrations and to determine its metabolic effects clearly." (PMID 31050684, 2019). "Individuals developing type 2 diabetes have spikes of sugar in their blood, and so their bodies often respond by trying to make large amounts of insulin." (PMID 31184302, 2019). "This review discusses different browning agents that have been discovered and studied so far in the context of diabetes type 2 treatment and/or effect of browning to glucose metabolism and insulin sensitivity." (PMID 30506389, 2019). "Similar dosages given continuously for 7 days were also shown to improve insulin action and secretion in diet- and age-induced Type 2 diabetic mice models." (PMID 30285464, 2019). "Type 2 diabetes mellitus (T2DM), characterized by chronic hyperglycemia caused by insufficient responses to insulin, is the most prevalent type of metabolic disorder, and it is estimated that over 344 million people are currently affected by this disease worldwide." (PMID 31312259, 2019). "Obesity-related type 2 diabetes is a progressive disorder and most patients eventually require treatment with insulin to control blood glucose levels as β cells in the pancreas lose their ability to produce insulin." (PMID 31024226, 2019). "A previous report has shown that treatment with AMP-dNM leads to improvement of glucose tolerance, reduction of hepatic steatosis, and enhanced response to insulin in rodent models of type 2 diabetes." (PMID 31013778, 2019).
type 2 diabetes (continued). "It has been observed that the higher prevalence of cases was found in the age group 40–59 years, predominantly the non-insulin dependent form of the condition otherwise known as type 2 diabetes." (PMID 31652912, 2019). "In the United States, addition to the >1 million people with type 1 diabetes, ∼30% of the >20 million people diagnosed with type 2 diabetes take insulin, half of these together with an oral agent or other therapy." (PMID 30357355, 2019). "First-line therapy for patients with type 1 diabetes is insulin therapy, whereas the medication options available for patients with type 2 diabetes are far broader, up to and including insulin therapy." (PMID 31781665, 2019). "New, second‐generation basal insulin analog therapies with improved pharmacokinetic/pharmacodynamic profiles have recently been approved for the treatment of type 1 and type 2 diabetes by the US Food and Drug Administration." (PMID 31294087, 2019). "Broccoli sprouts reduced the fasting blood glucose and serum insulin levels in type 2 diabetic patients." (PMID 31817632, 2019). "In individuals with type 2 diabetes where this effect is impaired, strategies that potentiate insulin secretion are vital in controlling postprandial blood glucose excursions." (PMID 31592446, 2019). "It has been reported that type 2 diabetic patients treated with insulin present increased levels of sTfR." (PMID 31296086, 2019). "Type 2 diabetes is a metabolic disease characterized by abnormally high blood glucose levels and cellular insulin resistance despite normal insulin production by the pancreas." (PMID 30939853, 2019). "Reduction in insulin sensitivity and postprandial hyperglycemia are the characteristics of type 2 diabetes." (PMID 31337381, 2019). "Type 2 diabetes (T2D) is the most common form of diabetes, a metabolic disorder characterized by hyperglycemia resulting from insufficient insulin production." (PMID 31116096, 2019). "Participants with type 2 diabetes using insulin were in target range 68% of the time, and type 1 diabetes 58% of the time." (PMID 31593545, 2019). "This discovery uncovers an unexpected, neomorphic insulin-sensitizing effect of FGF1 to treat type 2 diabetes and expands the functions of this classically known mitogen." (PMID 31920680, 2019). "Insulin secretion dysfunction of pancreatic beta cells is one of the most important mechanisms in the pathogenesis of type 2 diabetes." (PMID 30863781, 2019). "The conducted research allowed to find changes in metabolic homeostasis parameters in patients with type 2 diabetes after 6-month insulin therapy." (PMID 31195747, 2019). "The current study shows that eating competence is associated with a better quality of diet, a lower prevalence of new type 2 diabetes, abdominal obesity and metabolic syndrome, as well as better insulin sensitivity." (PMID 31905938, 2019). "In vivo assessment of adipose tissue insulin sensitivity in type 2 diabetes has been more limited; lower basal NEFA release has been reported in black women; however, no study has assessed insulin-stimulated suppression of NEFA release." (PMID 30729259, 2019). "Whereas in type 2 diabetes, the body is able to produce insulin, however it becomes resistant so that the insulin is ineffective." (PMID 30630432, 2019). "Type 2 diabetes is usually diagnosed by fasting glucose or HbA1c concentrations and several other blood markers (most prominently insulin) are known to play important roles in the pathophysiology." (PMID 30599058, 2019). "Type 2 diabetes, though primarily a disease characterized by decreased insulin sensitivity, also involves the destruction of insulin producing beta-cells during the later stages of the disease." (PMID 30837889, 2019). "Type 2 diabetes is a chronic metabolic disorder marked by hyperglycemia and results from an inadequate response to insulin." (PMID 30621667, 2019).
type 2 diabetes (continued). "The study involved 273 participants aged 18–70 years, with type 2 diabetes for at least 6 months, with HbA1c in the range of 7.0 to 10.0% (53 to 86 mmol/mol), taking at least 2 insulin injections per day for at least 3 months before the study." (PMID 30871141, 2019). "Both amyloid-β (Aβ) and insulin are amyloidogenic peptides, and they play a critical role in Alzheimer’s disease (AD) and type-2 diabetes (T2D)." (PMID 31652867, 2019). "We report the case of a 56 year-old Hispanic male with a 10-year history of type 2 diabetes who presented with abrupt onset of hyperglycemia resistant to escalating doses of intravenous insulin infusion (>2500 units daily)." (PMID 31827945, 2019). "Physical activity helps in weight loss or reduction in total fat, which ultimately helps to reduce blood pressure and to control blood glucose by increasing the insulin sensitivity, thereby preventing Type 2 diabetes." (PMID 31088447, 2019). "In many type-1 or insulin-treated type-2 diabetes patients, who cannot use an insulin pump, multiple daily injection insulin therapy with real-time CGM is a reasonable option." (PMID 31694629, 2019). "The objective of this study was to assess the cost-effectiveness of insulin glargine U100 compared to NPH insulin in patients with type-2 diabetes uncontrolled with non-insulin anti-diabetic agents alone in Hong Kong." (PMID 31303866, 2019). "TZDs enhance insulin sensitivity in several tissues and stimulate glucose tolerance and insulin sensitivity in patients with type 2 diabetes." (PMID 31827764, 2019). "We have found, in BAM and WEM with early type 2 diabetes and of similar BMI and age, comparable whole body, skeletal muscle, hepatic and adipose tissue insulin sensitivity despite lower VAT deposition and greater skeletal muscle mass in BAM." (PMID 30729259, 2019). "In type 2 diabetes, insulin insensitivity and insufficiency lead to a decrease in consumption of blood glucose by the liver, muscles, and adipose tissue thus, impaired insulin action directly affects the glucose production in the liver." (PMID 30944708, 2019). "A 58-year-old man with type 2 diabetes initiated subcutaneous insulin administration (SIA) after failure of oral antidiabetic treatment." (PMID 31711488, 2019). "The question on glucose lowering medication is also too broad to capture difference for those on insulin or other medications unique to type 2 diabetes." (PMID 30881349, 2019). "A detailed understanding of insulin signalling pathway is a prerequisite for developing new therapeutic strategies for obesity-related type 2 diabetes." (PMID 30948776, 2019). "Especially, the probiotic intervention improved the fasting blood glucose, insulin sensitivity, and systemic inflammatory and antioxidant status in type 2 diabetic (T2D) patients." (PMID 31950031, 2019). "Since the discovery of the pancreatic hormones insulin and glucagon, the prevailing understanding of type 2 diabetes development has circled around processes in the periphery, particularly in the pancreas." (PMID 31133864, 2019). "In patients with type 2 diabetes, tirzepatide was shown to reduce fasting glucose and insulin levels dose-dependently." (PMID 31443356, 2019). "IDH2 has been suggested as a potential therapeutic target in the treatment of type 2 diabetes and obesity due to its major role in modulating both insulin sensitivity and fuel metabolism in mice." (PMID 31234367, 2019). "Another study indicated that decrease in NLRP3 expression in adipose tissue is associated with reduction in inflammation and improvement of insulin-sensitivity in type 2 diabetes with obese patients." (PMID 31088900, 2019). "As the prevalence of obesity has risen during recent decades, so has the prevalence of type 2 diabetes, and with it the use of insulin." (PMID 30357355, 2019).